BRAF (B-Raf proto-oncogene, serine/threonine kinase)
Diseases named in the same sentence as BRAF in open-access papers (continued):
Sharing a sentence is not in itself a finding about the gene and the disease.
colorectal cancer (continued). "In line with this hypothesis, PTPRK-RSPO3-positive colorectal cancers are positive for KRAS or BRAF mutations and are microsatellite-stable." (PMID 29652830, 2018). "BRAF is a proto-oncogene that is frequently mutated in colorectal cancer." (PMID 30573851, 2018). "A recent study provided evidence that the BRAF-mutated group of colorectal cancer patients, mainly part of the CMS1 group, is heterogeneous and can be subdivided into two different subgroups that can be distinguished according to the pattern of gene expression." (PMID 29652830, 2018). "Landau and coworkers provided evidence that CDX2 loss was observed not only in MSI-H BRAF-mutated colorectal cancers, but also in a subgroup of MSS BRAF-mutated colorectal cancers, characterized by an aggressive clinical phenotype and increased Cytokeratin 7 expression expression." (PMID 29652830, 2018). "Similarly, the BRAF mutation was most common in the BRAF-mutant colorectal cancer cohort, with 93% of these patients having a confirmed BRAF mutation and the majority of patients having only mutations in BRAF (60%)." (PMID 28152546, 2017). "In support of this hypothesis, Yun and colleagues recently showed that intracellular reduction of DHA to AA killed glycolysis-driven KRAS and BRAF mutated colorectal cancer cells through inhibition of glycolysis resulting in ATP depletion." (PMID 28737676, 2017). "BRAF mutational status showed to be of influence on the incidence of colorectal cancer." (PMID 28125730, 2017). "The BRAF(p.V600E) mutation is found in approximately 10% of colorectal cancer patients." (PMID 29479053, 2017). "As PIK3CA mutations often coexist with KRAS and BRAF mutations in advanced cancers, including colorectal cancers, combination of AKT inhibition with panRAF inhibition are expected to induce at a minimum additive effects in both KRASmut/PIK3CAmut and BRAFmut/PIK3CAmut CRC models." (PMID 27999210, 2017). "SAC morphology was noted in 38% of MACs in our study, a result higher than previously reported (9.1%) for SAC in colorectal cancer, which might explain the high frequency of BRAF mutations and CIMP-positive status in MACs." (PMID 28422723, 2017). "In this study, we evaluated the frequencies and clinic-pathological characteristics of RAS mutation, BRAF mutation and DNA mismatch repair expression in Chinese patients with sporadic stage I-IV colorectal cancers, and studied the molecular heterogeneity of patients with different tumor site." (PMID 28416767, 2017). "Thus, VLX60 shows interesting properties of potential interest for development into a new anticancer drug, notably against BRAF mutated colorectal cancer." (PMID 28415818, 2017). "The impact of a drug that could selectively target BRAF-mutated colorectal cancer would be of great clinical benefit, since BRAF-mutation is associated with a poor prognosis and drug resistance." (PMID 28415818, 2017). "Interestingly, VLX60 exhibited a trend towards specific activity against both KRAS- and BRAF mutated tumor cells from patients with colorectal cancer." (PMID 28415818, 2017). "The V600E BRAF mutation clearly functions as a driver mutation in colorectal cancer." (PMID 29312543, 2017). "In addition, all our RAS-WT and BRAF-WT colorectal cancer patients were anti-EGFR resistant, a setting associated with MAPK pathway activation." (PMID 29108355, 2017). "However, other human malignancies (i.e., thyroid and colorectal carcinomas) are less sensitive to BRAF inhibitors (BRAFi), regardless BRAF mutational status." (PMID 29033690, 2017). "Similarly, different profiles of genetic mutations have also been observed in other types of human malignancies, for instance, there is a substantial difference in the BRAF mutation rate among white, black and Asian patients with colorectal cancer." (PMID 27029078, 2016). "The KRAS, NRAS and BRAF mutations in colorectal cancer are normally mutually exclusive." (PMID 26968814, 2016).
colorectal cancer (continued). "Moreover, in advanced colorectal cancer, BRAF mutations are associated with a poor prognosis and possibly resistance to treatment with monoclonal antibodies against EGFR (cetuximab and panitumumab)." (PMID 25902737, 2016). "Metabolomics revealed that vitamin C causes pentose phosphate pathway metabolites and glycolytic intermediates located up-stream of glyceraldehyde 3-phosphate dehydrogenase (GAPDH) to increase in KRAS and BRAF mutated colorectal cancer cells, whereas metabolites down-stream of GAPDH were decreased." (PMID 27616976, 2016). "However, different molecular classifications of colorectal cancer deduced by way of bioinformatic analyses of DNA aberrations and gene expression changes have identified more than one cluster involving BRAF mutation." (PMID 26496026, 2015). "Indeed, our data support the use of immunohistochemistry in detecting BRAF V600E mutation protein as an alternative to molecular testing in colorectal cancer." (PMID 25983749, 2015). "The predictive role of BRAF mutation in colorectal cancer is currently debated, but a recent meta-analysis indicated that BRAF mutation is a predictive biomarker of poor prognosis in mCRC patients treated by anti-EGFR monoclonal antibodies, especially in KRAS wild-type patients." (PMID 25983749, 2015). "Colorectal cancer cells with either a KRAS or BRAF mutation exhibited high expression levels of the glucose transporter-1 (GLUT1) gene and were able to survive in low glucose environments; whereas, the wild type cells exhibited low levels of GLUT1 and were not viable in low glucose conditions." (PMID 25856378, 2015). "We hypothesized it would be more commonly methylated and inactivated in serrated pathway colorectal cancers that are hallmarked by a BRAF V600E mutation and a methylator phenotype, compared to traditional pathway cancers that are BRAF wild type." (PMID 25613750, 2015). "However, for instance, in colorectal cancer, BRAF mutations status is an important and useful prognostic marker 23, despite its low prevalence rate of around 5%." (PMID 26310928, 2015). "Recent data show that apart from KRAS and BRAF mutations, mutations in genes related to colorectal cancer stem cells or cells that undergo EMT, such as CD133 and PLS3, might have therapy-predictive value and clinical significance." (PMID 25902072, 2015). "Although molecular biology remains the reference method for detecting KRAS mutation, immunohistochemistry could be an attractive method for detecting BRAF V600E mutation in colorectal cancer." (PMID 25983749, 2015). "Despite the revolu¬tion that occurred in the field of molecular marker research, only Serum CEA, Immunohistochemical analysis of mismatch repair proteins and PCR testing for KRAS and BRAF mutations have confirmed their clinical utility in the management of colorectal cancer." (PMID 24653752, 2014). "Therefore, it would be interesting to have on the market an IVD BRAF test such as the THxIDTM-BRAF assay to detect V600 mutation in colorectal cancer and non-small cell lung cancer." (PMID 25037456, 2014). "Our recent study on colorectal cancers in detailed subsites (from cecum to rectum) has shown that tumor molecular features (including BRAF mutation, MSI and CIMP-high) change along the bowel subsites, and that cecal cancers are associated with KRAS codon 12 and 13 mutations." (PMID 24885062, 2014). "The 5-year colorectal cancer-specific survival probabilities were 80.6% for cases with KRAS-wild-type/BRAF-wild-type tumors, 67.9% for cases with codon 12 mutations, 75.8% for cases with codon 13 mutations, 79.4% for cases with codon 61 mutations, and 76.7% for cases with codon 146 mutations." (PMID 24885062, 2014). "As depicted above, it becomes also clear that combined approaches, like the inhibition of the EGFR/BRAF-axis in BRAF V600E mutated colorectal cancers, could be used to overcome primary resistance in histological subtypes." (PMID 24879454, 2014).
colorectal cancer (continued). "In addition, BRAF V600E mutation was associated with poor prognosis in all groups of advanced colorectal cancer and was an independent prognostic factor for overall survival and cancer-specific survival in a pooled stage II/III cohort." (PMID 24298448, 2013). "Our hypothesis is that Cdx2 loss may be an important marker of other molecular changes associated with the serrated pathway to colorectal cancer, including BRAF mutation and high-level CIMP." (PMID 24130965, 2013). "Finally, in a meta-analysis that included 26 colorectal cancer studies, BRAF mutation was found to increase the risk of mortality (HR = 2.25, 95% CI: 1.82–2.83)." (PMID 24298448, 2013). "In humans, serrated colorectal cancers are associated with either BRAF or KRAS mutations." (PMID 23845441, 2013). "Recently, BRAF mutation testing has been introduced as a marker in differentiating sporadic colorectal cancers from Lynch syndrome: colorectal cancers having a BRAF mutation are very unlikely to have Lynch syndrome, whereas those without a BRAF mutation should be further evaluated using other tests." (PMID 24759670, 2013). "Intriguingly, strong Cten expression has been associated with KRAS/BRAF mutations in colorectal cancer, and this association was confirmed as being functionally relevant in colorectal and pancreatic cancers, where Cten has been identified as a downstream target of KRAS signaling." (PMID 24244691, 2013). "The lower rates of BRAF mutant colorectal cancer seen in the Asian cohort could thus indicate that BRAF mutations themselves may be less common in this group." (PMID 24066160, 2013). "We identified new BRAF mutation-specific methylation changes in colorectal cancer." (PMID 23324568, 2013). "The BRAF V600K mutation seems to be a rare event in colorectal cancer, at least in MSI-H tumors." (PMID 24298448, 2013). "BRAF V600E mutation is a marker of poor prognosis in colorectal cancer." (PMID 24298448, 2013). "In sporadic colorectal cancers, up to 15.7% of colorectal cancers have a BRAF mutation." (PMID 23202889, 2012). "The incidence of BRAF mutation V600E in colorectal cancer is 8–10%." (PMID 22792460, 2012). "The BRAF oncogene is mutated in 15% of sporadic colorectal cancers." (PMID 23110075, 2012). "In this study, we have reported the prevalence of somatic mutations in KRASPIK3CA, and BRAF genes among patients with advanced colorectal carcinoma from Sardinia, whose population shows genetic peculiarity due to geographical isolation and strong genetic drift." (PMID 22931052, 2012). "When separated by microsatellite instability status, BRAF mutations are present in 40–52% of colorectal cancers that arise through the microsatellite instability pathway (MSI) pathway (microsatellite unstable tumors), but only 5% of cancers are microsatellite stable." (PMID 21403829, 2011). "Mutations in the EGFR kinase domain predict sensitivity to the tyrosine kinase inhibitors gefitinib and erlotinib in lung adenocarcinoma, while activating point mutations in KRAS and BRAF confer resistance to the anti-EGFR monoclonal antibody cetuximab in colorectal cancer." (PMID 21943394, 2011). "Specific alterations of the EGFR gene, including copy number variations, and oncogenic activation of EGFR downstream effectors such as KRAS and BRAF had been previously reported as the genetic events underlying the response to cetuximab plus chemotherapy in colorectal cancer." (PMID 22152101, 2011). "Despite a strong association between CIMP and BRAF mutation in colorectal cancer, the hypothesis that BRAF mutation causes aberrant CpG island methylation has been highly controversial." (PMID 21738611, 2011). "In addition, an increasing number of tumors with either KRAS or BRAF mutation was observed with increasing age, in agreement with a recent report on young patients with colorectal cancer." (PMID 21103049, 2010).
colorectal cancer (continued). "We also considered the alternative hypothesis that promoter methylation of specific gene targets provides a favorable setting for the acquisition of BRAF mutation in CIMP+ colorectal cancers." (PMID 20027224, 2009). "Second, KRAS and BRAF genes are mutated in approximately 50% of colorectal cancers." (PMID 19014680, 2008). "A recent study indicated that MSI-H in the sporadic colorectal cancers may be part of a clinically distinct subgroup with a high incidence of BRAF mutation developed from serrated polyps." (PMID 18718023, 2008). "In microsatellite-unstable colorectal cancer cell lines, the effect of BRAF inhibition depended on whether the cell harboured a BRAF or a KRAS mutation." (PMID 19018267, 2008). "Associations with CIMP-high in BRAF-wild-type and BRAF-mutated colorectal cancers." (PMID 19002263, 2008). "Mutations in BRAF were identified in 8% (23/275) of colorectal cancers." (PMID 16403224, 2006). "Associations between BRAF mutation and clinicopathological features of colorectal cancer." (PMID 16403224, 2006). "BRAF mutation identifies a colorectal cancer subgroup with distinctive phenotypic properties independent of microsatellite instability status and thus could be a valuable marker for studies into the clinical properties of these tumors." (PMID 16403224, 2006). "Associations between BRAF mutation and molecular features of colorectal cancer." (PMID 16403224, 2006). "In addition, biomarkers such as RAS mutation, BRAF mutation, and PD-L1 expression are actively being investigated in relation to treatment options and prognosis in many gastrointestinal cancers, including colorectal cancer." (PMID 41375057, 2025). "Secondly, several previous trials investigating BRAF-mutated colorectal cancer primarily reported subgroup analyses from landmark studies with limited sample sizes, which could affect the reliability of the meta-analytical estimates; however, meta-regression also showed no substantial effect." (PMID 41355781, 2025). "The lack of this crucial information hinders the application of a treatment algorithm based on molecular biology, which could have influenced the selection of more personalized and effective treatments, especially in cases of colorectal cancer with BRAF mutations." (PMID 40149341, 2025). "After a multidisciplinary review by our oncology team, it was determined that the malignancy might be susceptible to BRAF and MEK inhibition, as well as their combination with anti-EGFR antibody therapy, following the same rationale as BRAF mutation-positive colorectal cancer." (PMID 40688855, 2025). "For instance, in colorectal carcinoma (CRC) with the BRAF V600E mutation (8% of CRC cases), treatment with CDK1 inhibitors significantly enhances the therapeutic efficacy of MEK inhibitors by reactivating caspase 8 activity." (PMID 39800748, 2025). "Therefore, both the three-drug combination (encorafenib, binimetinib, and cetuximab) for BRAF V600E mutation-positive colorectal cancer and the two-drug combination (encorafenib and cetuximab) are considered standard treatment options for BRAF V600E mutation-positive colorectal cancer." (PMID 38962037, 2024). "Another noteworthy mutation in colorectal carcinoma (CRC) involves the BRAF gene, which serves as a downstream molecule in the RAS signaling pathway." (PMID 38844562, 2024). "Interestingly, high ezrin expression was previously correlated with BRAFV600E mutation status in colorectal cancer since high ezrin immunohistochemical staining was found predominantly in BRAFV600E-mutated tumours (52%) in comparison with BRAF wild-type tumours (17%)." (PMID 37629086, 2023). "In prior studies, the BRAF V600E mutation in colorectal cancer was associated with an older age of onset, female sex, right‐side colon origination, poor differentiation and mucinous adenocarcinoma pathological phenotypes compared with BRAF wild‐type or BRAF non‐V600E mutant CRC." (PMID 36912150, 2023).
colorectal cancer (continued). "Colorectal cancers bearing BRAF mutations may be treated with specific BRAF inhibitors." (PMID 36295658, 2022). "However, mutations of SMAD4 occur only in a minority of BRAF mutated colorectal cancers and accumulation of alternative lesions may be needed to advance BRAF-associated carcinogenesis." (PMID 36079062, 2022). "Thus, inhibitors of the TGFβ pathway, should they become clinically available, could be candidates for combination therapies in BRAF mutated colorectal cancers." (PMID 36295658, 2022). "Interestingly, the activity of vitamin C against KRAS/BRAF mutated colorectal cancer might be useful to counteract tumor resistance to anti-epidermal growth factor receptor (EGFR) monoclonal antibodies (i.e., cetuximab, panitumumab)." (PMID 33804775, 2021). "However, when present, BRAF V600E-mutated colorectal cancers are associated with worse outcomes." (PMID 34535182, 2021). "Moreover, high ezrin expression has been associated with BRAF mutation in colorectal cancer." (PMID 34198671, 2021). "Although we do not present data in support of this hypothesis in this study, the frequency in which WNT16 is mutated in BRAF mutant colorectal cancers may provide an impetus for investigating whether WNT16 has a role in determining sensitivity to WNT-ligand inhibitors." (PMID 32384699, 2020). "Additionally, we showed that KRAS or BRAF mutation could be associated with improved prognosis in MSI-positive colorectal cancers." (PMID 30042065, 2018). "Although the relevance of mutant BRAF in the clinical setting is increasingly being acknowledged, the relatively low frequency of its occurrence requires further studies and larger experimental cohorts to secure its mutational status as a definitive biomarker for colorectal cancer." (PMID 30598662, 2018). "If the miRNA-dependent mechanisms underlying the oncogenesis of BRAF-mutant colorectal cancer are identified, this could lead to discovering novel molecular targets for therapy to improve the outcome of patients with colorectal cancer and even other cancers harboring BRAF mutations." (PMID 29115941, 2017). "The aim of this study was to identify miRNAs specifically dysregulated in BRAF-mutated colorectal cancer, which could lead to a better understanding of the molecular mechanisms underlying oncogenesis of this malignant subtype of colorectal cancer." (PMID 29115941, 2017). "Together, our results suggest that mutant BRAF may partly affect miR-193a-3p expression, but is unlikely to be a main direct cause of alterations in miR-193a-3p and its target gene expressions that are involved in tumorigenesis of colorectal cancer." (PMID 29115941, 2017). "Thus, further evaluation of VLX60 in BRAF mutated colorectal cancer is warranted." (PMID 28415818, 2017). "In the context of colorectal cancer, we present a method for constructing a surrogate biomarker that is able to predict with high accuracy whether a sample belongs to the “BRAF-positive” group, a high-risk group comprising V600E BRAF mutants and BRAF-mutant-like tumors." (PMID 28523274, 2017). "The similar BRAF mutation rates between serrated adenomas and hyperplastic polyps suggests that dysplasia may arise from hyperplastic polyps, resulting in the formation of serrated adenomas and potentially the development of colorectal carcinoma." (PMID 26910894, 2016). "Concerning the molecular classification of colorectal cancer and tumorigenesis, BRAF mutation is an early event hypothesized to give rise by way of oncogene-activated senescence to the development of sessile serrated adenomas (SSA) and to the hypermethylator phenotype." (PMID 26496026, 2015). "However, such cases may be considered for the combination therapy targeting both EGFR and BRAF, as had been described in a patient with BRAF V600E mutated colorectal cancer." (PMID 25415047, 2014). "Notably, the colorectal cancer had a BRAF V600E somatic mutation." (PMID 24782526, 2014).